TBCE (tubulin folding cofactor E)
Description:
Tubulin-folding protein; involved in the second step of the tubulin folding pathway and in the regulation of tubulin heterodimer dissociation. Required for correct organization of microtubule cytoskeleton and mitotic splindle, and maintenance of the neuronal microtubule network.
Synonyms: KCS1; pac2; HRD; KCS; PEAMO
Tractability: PROTAC: ubiquitination databases record sites on it; its protein half-life has been measured.
Gene: Protein-coding gene on chromosome 1 (235,367,360 to 235,452,443, forward strand). Ensembl gene ENSG00000284770.
Subcellular location: Cytoplasm; Cytoplasm, cytoskeleton
Pathways (Reactome):
Metabolism of proteins: Post-chaperonin tubulin folding pathway
Gene Ontology:
Molecular function: protein binding; alpha-tubulin binding; protein-folding chaperone binding
Biological process: microtubule cytoskeleton organization; mitotic spindle organization; post-chaperonin tubulin folding pathway; protein folding; tubulin complex assembly
Cellular component: cytoplasm; microtubule; cytoskeleton
Genetic constraint (gnomAD): Loss-of-function variants: 52 observed, 75.46 expected, observed/expected ratio (o/e) 0.69, 90% interval 0.55 to 0.87. The upper end of that interval is the gene's LOEUF score, 0.87, which puts it in group 3 of 6, group 1 being the genes least tolerant of losing a copy. Missense variants: 617 observed, 645.86 expected, observed/expected ratio (o/e) 0.96, 90% interval 0.89 to 1.02. Synonymous variants: 234 observed, 252.07 expected, observed/expected ratio (o/e) 0.93, 90% interval 0.83 to 1.03.
Gene-disease validity (ClinGen):
ClinGen rates the evidence that TBCE causes each of these diseases.
encephalopathy, progressive, with amyotrophy and optic atrophy (autosomal recessive): Moderate.
Homologues: Orthologues: macaque TBCE (93% identical), chimpanzee TBCE (93% identical), rabbit TBCE (83% identical), pig TBCE (82% identical), dog TBCE (81% identical), guinea pig TBCE (79% identical), rat Tbce (75% identical), mouse Tbce (74% identical), tropical clawed frog tbce (57% identical), zebrafish tbce (51% identical), Drosophila melanogaster Tbce (30% identical), Caenorhabditis elegans tbce-1 (29% identical). Paralogues in human: TBCEL (21% identical).
Diseases named in the same sentence as TBCE in open-access papers:
TBCE is named in the same sentence as 45 diseases in open-access papers, as found by Europe PMC text mining. Sharing a sentence is not in itself a finding about the gene and the disease. The quoted sentences say what the papers report.
hypoparathyroidism (6 papers, 2013 to 2025). Hypoparathyroidism is an endocrine disorder in which the parathyroid glands in the neck do not produce enough parathyroid hormone (PTH). "The second exception is the p.S52_G55del mutation in the TBCE gene causing hypoparathyroidism and mental retardation that originated among Bedouins in Saudi Arabia who are at the origin of the Israeli Bedouin Arabs." (PMID 28302154, 2017). "For example, knockdown of TBCE/tbce, implicated in hypoparathyroidism-retardation-dysmorphism syndrome, showed structural defects of developmental origin." (PMID 24204314, 2013). "It has been postulated that TBCE and microtubule assembly may play a crucial role in the development of the parathyroid gland, which may explain the constant association of TBCE mutations responsible for this syndrome with hypoparathyroidism." (PMID 39246904, 2024). "TBCE-deficient mice (pmn/pmn) do not demonstrate hypoparathyroidism, but neurological abnormalities are present, as TBCE is important for axonal tubulin routing from the Golgi apparatus and, in its absence, axonal degeneration occurs." (PMID 35935360, 2022). "The precise molecular mechanisms through which TBCE mutations cause hypoparathyroidism is still not clear, as the gene product is nearly absent in normal mature parathyroid tissue." (PMID 35935360, 2022).
hypoparathyroidism-retardation-dysmorphism syndrome (4 papers, 2017 to 2025). "The TBCE gene is involved in neurodevelopment disorders such as Hypoparathyroidism-Retardation-Dysmorphism Syndrome (OMIM: 241,410), which is associated with micropenis and cryptorchidism." (PMID 40037090, 2025). "Biallelic variants of TBCE are associated with Hypoparathyroidism-Retardation-Dysmorphism Syndrome and Kenny-Caffey Syndrome (OMIM 604934)." (PMID 35432193, 2022). "A six-month-old male with Sanjad-Sakati syndrome, confirmed by genetic mutation in TBCE (tubulin-specific chaperone E) gene, had HPT (PTH <0.6 pmol/L) and was stable on standard doses of ACD, though had already developed signs of nephrocalcinosis." (PMID 28993435, 2017).
22q11.2 deletion syndrome (2 papers, 2021 to 2023). 22q11.2 deletion syndrome (DS) is a chromosomal anomaly which causes a congenital malformation disorder whose common features include cardiac defects, palatal anomalies, facial dysmorphism, developmental delay and immune deficiency. "Although 22q11.2 deletion syndrome and chromosomal abnormalities were ruled out in this case, a genetic etiology could not be ruled out as the patient was not evaluated for other genetic abnormalities such as NEBL, TBCE, FAM111A, CASR, and GNA11 mutations." (PMID 36865979, 2023).
bowel obstruction (1 paper, 2022). "These may be related to TBCE loss of function in multiple organs or to the disrupted calcium and phosphor homeostasis that, in turn, may be the first step in multiple cascades, culminating in seizures, bowel obstruction, nephrolithiasis, and susceptibility to infections." (PMID 35935360, 2022).
hereditary spastic paraplegia (1 paper, 2013). Hereditary spastic paraplegias (HSP) comprise a genetically and clinically heterogeneous group of neurodegenerative disorders characterized by progressive spasticity and hyperreflexia of the lower limbs. "It is interesting to note that mutation of TBCE in mice results in a progressive motor neuropathy while mutations in spastin are the cause of the most common form of hereditary spastic paraplegia in humans, likely through disruption of axonal transport." (PMID 23840848, 2013).
renal tubular dysfunction (1 paper, 2014). "TBCE and CA2 are not functionally associated, but both genes are associated phenotypically with renal tubular dysfunction (HP:0000124) and increased bone mineral density (HP:0011001)." (PMID 25420641, 2014).
TBCE also shares sentences with these, for which no sentence is quoted: infection (4 papers); tumor (3); Intellectual disability (2); leiomyosarcoma (2); ovarian carcinoma (2); Alzheimer disease (1); amyotrophic lateral sclerosis (1); Angelman syndrome (1); APECED) syndrom (1); basal cell nevus syndrome (1); blepharocheilodontic syndrome (1); breast carcinoma (1); cancer (1); chordoma (1); COVID-19 (1); cryptorchidism (1); dedifferentiated liposarcoma (1); distal spinal muscular atrophy (1); eosinophilia (1); epilepsy (1); Fanconi anemia (1); Floating-Harbor syndrome (1); gynecological cancer (1); gynecological tumors (1); hepatocellular carcinoma (1); incontinentia pigmenti (1); intestinal tumors (1); Kenny-Caffey syndrome (1); Micropenis (1); myxofibrosarcoma (1).
A further 9 diseases each share a sentence with TBCE in 1 paper.